NPY (neuropeptide Y)
Diseases named in the same sentence as NPY in open-access papers (continued):
Sharing a sentence is not in itself a finding about the gene and the disease.
Anxiety (continued). "Individuals vary in their expression of NPY, and low levels of NPY have been associated with the development of anxiety, depression, and posttraumatic stress disorder (PTSD)." (PMID 34867217, 2021). "Future work should examine the role of NPY in the activity of the salience network and how such network alterations impact risk for anxiety and depression." (PMID 34867217, 2021). "NPY polymorphisms, such as the −399G allele in the NPY promoter region, have been implicated in anxiety and depression." (PMID 32246073, 2020). "Despite that we solely observed associations of PP with anxiety and age with NPY and PP in men, suggesting a possible influence of sex hormones on the NPY system." (PMID 33192409, 2020). "As there was no induction of mature NPY polypeptides in these mutants and the mutants exhibited similar phenotypes throughout the study, NPY deficiency caused anxiety under stressful conditions." (PMID 32246073, 2020). "Acute stress caused the NPY-KO zebrafish to exhibit anxiety behaviours such as freezing, decreasing movement and velocity, and swimming along the side of the tank." (PMID 32246073, 2020). "In view of the critical role of both the BNST and the NPY system in anxiety-like and stress-related behaviors and associated disease states, we identified NPY-expressing neurons in BNST and compared their properties with those that lack NPY expression." (PMID 30455634, 2018). "For instance, NPY-deficient mice display hypolocomotion and increased anxiety-like behavior measured in the acoustic startle response test, open field, elevated plus maze, and light-dark box tests, with males being more affected than females." (PMID 30131681, 2018). "Taken together, our results show that loss of GAD67 from NPY+ cells causes reduced open arm time in the elevated plus maze, and increased thigmotaxis in the open field, suggesting a mild increase in anxiety-like behavior in adolescent mice." (PMID 30024942, 2018). "NPY plays a role in a variety of basic physiological functions and is also implicated regulating cognition, including anxiety, learning, and memory." (PMID 28143489, 2017). "NPY is also associated with neuropsychiatric disorders such as anxiety, depression, and bipolar disorder." (PMID 25161819, 2014). "NPY expression has been implicated in neuronal functions, anxiety, memory consolidation and cognition." (PMID 24146943, 2013). "Yet, abstinence from nicotine induced anxiety-like behavior that was associated with a decreased ratio of NPY to CRF in the amygdala, suggesting an allostatic change in both stress and anti-stress neuropeptide systems." (PMID 23761766, 2013). "In any case, the anxiolytic effect of NPY in the amygdala is linked to the function of NPY-ir interneurons, since the number of these neurons is correlated closely with anxiety-like behavior." (PMID 22527118, 2013). "This interpretation is in general agreement with studies showing stress resilience in rats over expressing NPY, or increased susceptibility to stress and anxiety in NPY knockout mice." (PMID 23483949, 2013). "NPY (Neuropeptide Y) is associated with depression and anxiety neurotransmission in hippocampal malfunctions in depression, and antidepressive treatment (wheel running) normalizes its level." (PMID 16995950, 2006). "Neuropeptide Y has emerged as a prominent research focus; evidence indicates that it rapidly activates neurons with neuropeptide Y receptors in response to stress, thereby alleviating anxiety—a process associated with reduced activity within the HPA axis." (PMID 41415252, 2025). "In the rodent hippocampus, decreased levels of NPY may be associated with impaired cognition, and Npy knockout mice have demonstrated anxiety-like behavior in the open field test (OFT), elevated plus maze (EPM), and light–dark box." (PMID 40178780, 2025).
Anxiety (continued). "Similarly, the anxiolytic effect of NPY involves suppression of the anxiety-associated genes (Orx and Cck) and catecholamine production (gr, mr, th1, and th2) in the brain." (PMID 38474180, 2024). "Moreover, fasting diminishes the ability of CeA projections in the BNST to suppress food intake, and NPY-deficient mice fail to decrease anxiety in order to promote feeding." (PMID 38937485, 2024). "Indeed, NPY has similarities with GABAergic agents such as benzodiazepines in reducing CNS activity, and low levels of NPY have been associated with psychiatric disorders including anxiety and depression." (PMID 37630771, 2023). "Moreover, levels of genes associated with anxiety were notably higher in the NPY-KO strain than in the wildtype fish." (PMID 36829752, 2023). "The functional polymorphisms in NPY may therefore predispose individuals to anxiety and low mood, which are recognized features of the acute sickness response to infection and PIFS." (PMID 35959390, 2022). "Our results suggest that NPY may play a role in network regulation, and this should be a focus of future studies on neurobiological risk factors for anxiety and mood disorders." (PMID 34867217, 2021). "The processes by which the association between anxiety and epilepsy arise might be a function of changes in neurotransmitter systems which are relevant in both conditions such as that involving NPY." (PMID 34025410, 2021). "Cold stress caused anxiety behaviour in the NPY-KO zebrafish." (PMID 32246073, 2020). "This hypothesis is based on our results which confirmed the association of prenatal androgen treatment with anxiety and reduced NPY and PV immunoreactivity in CA1 hippocampal region." (PMID 31281833, 2019). "Neuropeptide Y is the most abundant neuropeptide in the central and peripheral nervous systems in mammals and has been implicated in different activities ranging from the control of anxiety to angiogenesis and cardiovascular function." (PMID 30935107, 2019). "Under the normal physiological response, the brain homeostatically mobilizes anti-CRF (anti-stress) mechanisms such as N/OFQ and neuropeptide Y to curb EtOHW-induced stress response, while the imbalance tilted toward pro-stress seems to underlie EtOHW-induced anxiety." (PMID 31234859, 2019). "Additionally, NPY itself has been shown to have anxiolytic effects, and loss of NPY+ interneurons enhances anxiety behaviors." (PMID 30024942, 2018). "Understanding the relationship between central nervous 5-HT availability and peripheral NPY concentrations is of particular importance with regards to the neurobiology of stress-associated neuropsychiatric disorders, for example anxiety and depressive disorders." (PMID 29751614, 2018). "There is an abundance of literature suggesting that NPY may be inversely associated with levels of stress, hunger, anxiety, depressed mood, alcoholism, and epilepsy." (PMID 29751614, 2018). "Considering that Mic-1/Gdf15 deficiency might result in up-regulation of NPY, it is interesting to note that NPY overexpressing mice show similar behavioural characteristics to Mic-1 KO mice including decreased anxiety." (PMID 28081177, 2017). "Reduced NPY expression, both mRNA and protein, may constitute a risk for depression and anxiety-related behaviors." (PMID 28824541, 2017). "Restoring CREB function to optimal level or enhancing NPY signaling in the central AMG prevented the onset of anxiety-like behaviors, while alcohol-associated anxiety disorders can be mimicked by pharmacological blockade of PKA in ethanol-naïve-preferring rats or non-preferring rats." (PMID 27766083, 2016). "Therefore, EC facilitated a coping response against a fear associated cue in a PTSD animal model and reduced anxiety by differentially activating serotonergic and NPY-ergic systems." (PMID 26016844, 2015).
Anxiety (continued). "This beneficial influence of WAS is consistent with its ability to counteract the effects of DSS-induced colitis to reduce social interaction and elevate anxiety in association with increased plasma corticosterone and hypothalamic neuropeptide Y mRNA expression." (PMID 26217204, 2015). "Nonetheless, therapies that increase NPY selectively in the brain may prove effective in treating anxiety or depressive disorders and decrease cardiovascular risk by reducing sympathetic activity." (PMID 25206349, 2014). "Since IBD is associated with an increased risk for anxiety and mood disorders, we focused in particular on three messenger molecules that are known for their role in the regulation of anxiety and mood: NPY, BDNF, and CRF." (PMID 25414650, 2014). "Reduced amygdala NPY has been linked to increased anxiety and since low doses of alcohol may increase NPY, alcohol-induced NPY expression may be a possible mechanism for the anxiolytic effect of alcohol." (PMID 25278825, 2014). "It has been shown that decreases in CREB phosphorylation and NPY expression in the central amygdala might be associated with anxiety-like behaviors in models of ethanol withdrawal in rats." (PMID 22163304, 2011). "Previously, we have discussed that neuropeptide Y and related peptides might be involved in the association between anxiety/depression and decrease in blood pressure." (PMID 21797992, 2011). "Therefore, the authors of the present study suggest that the increased anxiety and physical activity observed in patients with AN might be partially associated with a decreased level of NPY." (PMID 33670342, 2021). "Furthermore, good insight in interconnection between the alterations in emotional processing (expressed as depression, anxiety or the clinical phenotype of anxious depression) and single nucleotide polymorphism (SNP rs16147) in the NPY gene was found using fMRI in amygdala." (PMID 28582442, 2017). "GO analysis further highlighted alterations in key regulators of anxiety-related neurotransmission, including neuropeptide Y and L-DOPA receptor activities, as well as phenylethanolamine N-methyltransferase activity." (PMID 41536523, 2026). "Nonetheless, our findings confirmed a causal link between peri-LCNPY activity and the regulation of anxiety-like behaviors, where local Y1R-mediated NPY signal tempers LCNE firing, promoting anxiolysis." (PMID 40700482, 2025). "These latter findings indicate that NPY exerts strong neuromodulatory control over the LC to drive bidirectional changes in anxiety-like behavior." (PMID 40749333, 2025). "Neuropeptide Y has previously been implicated in ADHD and emotional dysregulation, including anxiety." (PMID 41440000, 2025). "Neuropeptide Y (NPY) levels, a neuropeptide commonly found in the brain, have been observed to be reduced in conditions such as depression, chronic stress, and anxiety." (PMID 40636869, 2025). "A pivotal investigation demonstrated that transferring gut microbes from individuals with ulcerative colitis led to reduced NPY expression in the colon and, at the same time, gave rise to anxiety- and depression-like behaviours in mice." (PMID 41462683, 2025). "Our data are in conflict with an earlier study in rats, where pharmacologically applied NPY within the LC vicinity resulted in reduced anxiety via Y2Rs." (PMID 40700482, 2025). "In accordance with the Y1R-dependent control of peri-LCNPY neurons over LCNE excitability, we here demonstrate that the anxiety-relieving effects of local NPY release in the LC are mediated via Y1Rs." (PMID 40700482, 2025). "Variations in neuropeptide Y (NPY) gene expression affect anxiety reduction and stress tolerance, with people carrying low-NPY variants showing heightened emotional responses to threatening stimuli and reduced pain tolerance." (PMID 40806735, 2025).
Anxiety (continued). "Recently, a study employing intersectional manipulations of peri-LC NPY cells showed that endogenous chemogenetically evoked NPY release in the LC reduces baseline anxiety-related behaviors in the EPM and the NSF tasks, an effect that is mediated by Y1Rs." (PMID 40749333, 2025). "Understanding the effects of endogenous NPY signaling is critical as pharmacologically applied NPY engages distinct NPY receptors, resulting in dose-dependent, opposing regulation of anxiety-like behaviors." (PMID 40700482, 2025). "Oral administration of Enterococcus mundtii, belonging to Enterococcaceae, resulted in reduced levels of anti-depressive neuropeptide Y in the colon, plasma, and hippocampus, leading to anxiety and depression-like behavior in mice." (PMID 39870972, 2025). "Other neurochemical theories pinpoint a dense concentration of neuropeptide Y (NPY) in anxiety circuits, believed to be involved in fear memory consolidation." (PMID 39025836, 2024). "Neuropeptide Y (NPY), another highly conserved neuropeptide, contributes to controlling energy homeostasis, anxiety and sleep; exhibiting dual impact on sleep–wake behaviours in mammals." (PMID 38324048, 2024). "Converging preclinical evidence supports NPY’s role in modulating the stress response and regulating anxiety in animal models." (PMID 37629588, 2023). "NPY plays a role in regulating various systems throughout the body such as memory, anxiety, fear, and stress." (PMID 36829752, 2023). "Food intake, sexual behavior, information processing, cognition, learning, and memory, as well as stress and anxiety, are all significantly regulated by NPY and NPY receptors." (PMID 36829752, 2023). "In accordance with these findings, NPY has been found to mediate the anxiolytic effect of agmatine, a neurotransmitter involved in regulating anxiety, in rats." (PMID 36829752, 2023). "Neuropeptide Y knockout exhibited anxiety-like behaviors, such as freezing and swimming in the wall area under cold stress, but Ninjinyoeito treatment improved these behaviors." (PMID 37324500, 2023). "In this study, from clinical and basic research perspectives, we compared their effects on anxiety and sociability in NPY-KO zebrafish." (PMID 37324500, 2023). "By contrast, we found that Y2 receptor activation mildly increased anxiety-like behaviors, similar to previous reports on the anxiogenic effects of NPY through Y2 receptors in the amygdala and lateral ventricles." (PMID 37231359, 2023). "Ninjinyoeito treatment also improved anxiety-like behaviors of neuropeptide Y knockout in the novel tank test." (PMID 37324500, 2023). "Neuropeptide Y plays an important, albeit complex, role in regulating responses to stress and modulating fear and anxiety-related behaviors." (PMID 37629588, 2023). "In the present study, we surprisingly revealed that microinjection of NPY in VEH mice induced anxiety." (PMID 37231359, 2023). "This study compares the effects of NYT, HET, and JTT on psychiatric symptoms, such as anxiety and sociability, using NPY-KO zebrafish, a suitable animal model for anxiety and low sociability." (PMID 37324500, 2023). "NPY controls anxiety primarily via the activation of postsynaptic Y1R and Y5R and of presynaptic Y2R, inducing anxiolytic and anxiogenic effects, respectively." (PMID 37630771, 2023). "The role of the NPY system in the anxiolytic action of allopregnanolone (ALLO), a steroid associated with the regulation of anxiety, was demonstrated in a mouse model where the VCT was utilized to quantify the anxious behavior by counting the number of shocks." (PMID 36829752, 2023). "The NPY-KO zebrafish showed low sociability in the three-Chambers test and exhibited anxiety-like behaviors such as freezing under acute stress." (PMID 37324500, 2023).
Anxiety (continued). "Other neurochemical theories have suggested the significant involvement of the neuropeptide Y (NPY), given its a dense concentration in anxiety circuits, which has been thought to be involved in the consolidation of fear memories." (PMID 36793941, 2023). "Recently, neuropeptide Y-knockout (NPY-KO) zebrafish were established as models for anxiety-like and low social behavior." (PMID 37324500, 2023). "Initial (phase I) clinical evidence indicates that a high dose of intranasal NPY reduces anxiety in individuals with PTSD, and there is another active PTSD trial underway (NCT04071600)." (PMID 36623804, 2023). "Serum NPY levels were found to be lower in patients with anxiety and depression compared to healthy controls." (PMID 36829752, 2023). "Under acute stress, the NPY-KO zebrafish exhibit anxiety-like behaviors including freezing, increased swimming in the wall area of the test tank, and erratic movement." (PMID 37324500, 2023). "NPY is involved in the regulation of emotional behaviors such as social and anxiety behaviors in a mammal." (PMID 37324500, 2023). "Another study of NPY comparing CFS patients with HC patients showed that NPY was significantly increased in CFS patients, which means that the reduction of NPY level leads to the relieve of anxiety and depression." (PMID 35847786, 2022). "With systemic stress, NPY is released, regulates endocrine, behavior, stress, anxiety, appetite, and circadian rhythms, and functions in defecation and food intake." (PMID 35592257, 2022). "In the CNS, NPY fulfils several physiological functions related to feeding behavior, learning and memory, anxiety control, and circadian rhythm, to name just a few." (PMID 35409198, 2022). "In particular, it was anticipated that the low NPY-producing diplotype (HB1/HB1) previously shown to confer high-risk for stress, anxiety, and low mood would be associated with mood disturbance during and after acute infection." (PMID 35959390, 2022). "The human neuropeptide Y (NPY) acts through G-protein coupled receptors and is involved in food intake, stress response, anxiety, and memory retention." (PMID 35165283, 2022). "The widely distributed CNS, Neuropeptide Y (NPY), regulates many diverse physiological purposes such as stress response, anxiety, and cognition." (PMID 35250569, 2022). "Neuropeptide Y is involved in the modulation of several different effector systems, such as water and food intake regulation, control of mood and anxiety-related behavior, as well as vascular vasoconstriction and central autonomic functions." (PMID 36263121, 2022). "Although this study is only about anxiety and stress response, it also has important reference significance for the study of schizophrenia and NPY." (PMID 36339882, 2022). "Through its receptors, NPY has many known roles, including the regulation of vasoconstriction, feeding behavior, anxiety, cell proliferation, and immune cell activation and recruitment." (PMID 35418942, 2022). "An increasing number of different neuropeptide systems (e.g., galanin, cholecystokinin, and NPY) have been shown to modulate fear and anxiety in rodents and humans." (PMID 34072275, 2021). "In contrast to CRF’s role in promoting anxiety/stress, intra-LS administration of neuropeptide Y decreases anxiety-like behaviors, evidenced by increased social interaction and other active coping behaviors." (PMID 34764187, 2021). "The results showed that the NPY level was slightly increased in the ACS with comorbid anxiety group compared with the ACS group, but the difference was not significant." (PMID 34145340, 2021). "The neuropeptide Y (Npy) is also present in inhibitory interneurons throughout the brain and regulates behavioral responses, especially those related to anxiety and fear." (PMID 33897403, 2021).